NRG1 (neuregulin 1)
Diseases named in the same sentence as NRG1 in open-access papers (continued):
Sharing a sentence is not in itself a finding about the gene and the disease.
tumor (242 papers, 2005 to 2026). "Collectively, these findings support that NRG1 functions as a tumor suppressor in CRC, where low expression is associated with poor prognosis and high expression correlates with improved survival." (PMID 41190067, 2025). "The analysis result showed that the serum PSA levels were positively associated with the serum NRG1, NRG1 in biopsy tumor tissue and relative NRG1 mRNA levels in tumor tissue." (PMID 40740239, 2025). "Subsequently, the levels of NRG1 in blood and tumor tissue were detected using enzyme-linked immunosorbent assay, western blotting, and qPCR." (PMID 40740239, 2025). "The findings from our analysis reveal important insights into the tumor biology associated with NRG1 fusions." (PMID 40730881, 2025). "The ROC curve analysis revealed that relative NRG1 mRNA expression in tumor tissue exhibited the highest diagnostic accuracy for predicting CRPC progression, with an AUC of 0.78 (95% CI: 0.72-0.85), sensitivity of 57.65%, and specificity of 89.47%." (PMID 40740239, 2025). "NRG1 fusion-positive tumors often exhibit a low tumor mutation burden and low PD-L1 expression, potentially contributing to resistance against immune checkpoint inhibitors." (PMID 38957319, 2024). "The limited data pertaining to a predominant histology, molecular subgroup, or hormonal status associated with NRG1 fusion in specific tumor types necessitates further investigation in terms of effective screening strategies." (PMID 38173003, 2024). "Recent research has highlighted NRG1’s pivotal role in the genesis and progression across a spectrum of tumors, influencing molecular perturbations across various tumor-associated signaling pathways." (PMID 38957319, 2024). "NRGs are encoded by four genes (NRG1-4) and have mitogenic and pro-apoptotic characteristics, giving them dual oncogenic and tumor suppressor functions." (PMID 37389721, 2023). "As such, NRG1-encoded proteins are oncogenic as they are mitogens capable of promoting tumor growth." (PMID 36707514, 2023). "Examples of receptors overexpressed in SCLCs included ERBB3 (tumor ligands NRG1, NRG2) and GDNF receptor 1 encoding GFRA1 (ligand NCAM1)." (PMID 36271074, 2022). "In order to obtain a signature of genes linked with NRG1 expression in tumour stromal fibroblasts, we selected those genes with the strongest correlation with NRG1 (Pearson r > 0.8), and with a log2FC > 2 in high- vs low-NRG1 CAFs." (PMID 33692466, 2021). "The reduction of connexon formation induced by NRG1 in SkBr3 cells supports the tumor protective effect since the loss of GJIC is known as a typical factor towards tumor stabilization." (PMID 30836676, 2019). "While NRG1 loss was observed in only 7 of the tumor samples from 526 GBM patients in TCGA, ERBB4 loss was observed in 81 samples." (PMID 29342193, 2018). "Of note, a KIF13B/NRG1 fusion was identified in a liver metastasis and associated with tumor progression." (PMID 30618566, 2018). "Both AlbT3 and A17LKO mice showed in the tumor tissue increased expression of the unclipped ErbB4 isoforms and decreased level of NRG1 suggesting that the downregulated signals mediated by this are associated to decreased tumor progression and areas." (PMID 28751722, 2017). "Lastly, an analysis of patient tumor samples reveals an association between RNA expression levels of NRG1, and two EGFR ligands amphiregulin (AREG) and transforming growth factor α (TGFα)." (PMID 28723928, 2017). "We also demonstrated that Nrg1, which has been implicated in transcriptional regulation, heterochromatin formation, genomic stability, cell-cycle progression and tumor progression, is a direct target of miR-125a-3p." (PMID 25560389, 2015). "Furthermore, NRG1 also activates tumor-associated fibroblasts (CAFs) or immune cells through paracrine mechanisms, promoting local androgen synthesis or inflammatory cytokine release, thus indirectly sustaining AR activity." (PMID 40740239, 2025).
tumor (continued). "The cutoff for relative NRG1 mRNA expression in tumor tissue (1.353) provides the highest diagnostic performance, with specificity of 89.47% and sensitivity of 57.65%, rendering it valuable for confirming CRPC in challenging cases and refining risk stratification." (PMID 40740239, 2025). "Specifically, KRAS-mutant tumors exhibited decreased NRG1 expression and hyperactive SG formation, indicating that oncogenic mutations may intersect with subcellular organizational dynamics to sculpt tumor behavior." (PMID 41190067, 2025). "Our results show that tumor-associated myeloid cells (CD68+) may contribute to the NRG1 pool seen in these tumors." (PMID 39210279, 2024). "Furthermore, the association of NRG1 fusions with adverse clinical outcomes, such as tumor recurrence, metastasis, chemotherapy resistance, and poor prognosis, emphasizes the urgent need for targeted therapeutic approaches." (PMID 38957319, 2024). "Furthermore, it is also believed that NRG1 is associated with the immune microenvironment of the tumor, thereby impacting the infiltration and functionality of immune cells." (PMID 38331905, 2024). "However, more in-depth studies are essential to fully comprehend the molecular mechanisms underlying NRG1 fusions and their impact on tumor development and treatment response." (PMID 38957319, 2024). "Heregulin isoforms encoded by NRG1 promote tumor growth and induce metastasis." (PMID 35060926, 2022). "NRG1 is also known to activate tumour‐associated epithelial cells, thereby facilitating metastasis." (PMID 34288395, 2021). "Given the now widely used next-generation sequencing (NGS) diagnostic tool, which detects such mutations in tumor tissues and in blood, it becomes a matter of whether NRG1 can be a clinically targeted mutation." (PMID 34680187, 2021). "We identified four NRG1 fusions of the form (geneA)-NRG1, that were both predicted from DNA rearrangement junctions and found in RNA sequence reads: WRN-NRG1, FAM91A1-NRG1, ARHGEF39-NRG1, and ZNF704-NRG1 (which also gives tumour subtypes and other known driver mutations)." (PMID 33413557, 2021). "All this contributes to the growing amount of evidence that not only could NRG1 represent a targetable alteration, but also that its presence increases the risk of different types of tumor; it could, potentially, be used as a genetic assessment in liquid biopsies." (PMID 34680187, 2021). "Taken together, NRG1 preserved cardiac function during anthracycline treatment while maintaining anti-tumor efficacy." (PMID 42196592, 2026). "This study evaluated daily recombinant NRG1 co-administered with DOX in 4T1-tumor-bearing female BALB/c mice." (PMID 42196592, 2026). "NRG1 secreted by CAFs acts in a paracrine manner to sustain tumor growth and confer resistance to both enzalutamide and ADT through AR-independent mechanisms, contributing to castration resistance." (PMID 41228234, 2025). "The development of KRASG12C inhibitors, FGFR inhibitors, and NRG1-targeted therapies marks a significant step forward in tumor-agnostic treatments." (PMID 41179283, 2025). "Our results revealed that NRG1 expression is significantly lower in tumor tissues compared to normal tissues in TCGA, GPL570_CRC and GPL96_CRC cohort." (PMID 41190067, 2025). "The correlation among serum NRG1, NRG1 in biopsy tumor, and relative NRG1 mRNA levels in tumor tissue were analyzed using Pearson analysis." (PMID 40740239, 2025). "Among the 85 patients who progressed to CRPC, and 152 patients who did not progress to CRPC, the levels of NRG1 in serum and biopsy tissues, as well as the relative NRG1 mRNA levels in tumor tissue, were detected before the initiation of ADT." (PMID 40740239, 2025). "The results showed that intratumoral injection of NRG1 significantly increased tumor volume and weight after chemotherapy." (PMID 41213930, 2025).
tumor (continued). "The value of NRG1 levels in serum, biopsy tissue, and relative NRG1 mRNA in tumor tissue of PC patients before ADT for predicting CRPC progression within one year after ADT was investigated using ROC analysis." (PMID 40740239, 2025). "Further studies revealed that CAFs activate human epidermal growth factor receptor 3 (HER3) in tumor cells by secreting NRG1, and pharmacological blockade of the NRG1-HER3 axis can inhibit the development of PCa hormone resistance." (PMID 40438694, 2025). "This was evident in the registrational phase II eNRGy trial of patients with advanced NRG1 fusion-positive cancer in any tumor type that received zenocutuzumab." (PMID 41091579, 2025). "The results showed that the levels of serum NRG1, NRG1 protein in tumor tissues and NRG1 mRNA in tumor tissue, were all significantly higher in CRPC patients before receiving ADT treatment, compared to NCRPC patients." (PMID 40740239, 2025). "Using multiple in vivo and in vitro models, Zhang and colleagues reported that CAFs promote resistance to antiandrogen therapy and identified NRG1 as a key secreted mediator acting through HER3 activation in tumor cells." (PMID 41514658, 2025). "The group generated circulating tumour cell organoids from patients and identified neuregulin 1 (NRG1)-ERBB2 receptor tyrosine kinase 3 (ERBB3/HER3) signalling as a key survival pathway for cells through multiomics." (PMID 40650785, 2025). "By contrast, module 2 and 3, which were only downregulated in EGF-stimulated SHP2WT cells, contained several tumor suppressors, such as NRG1, MAP3K1, CAVIN3, EPHA3/7, CTNNA1/3, and NOTCH3." (PMID 40631144, 2025). "Meanwhile, NRG1 levels in tumor tissue also demonstrated robust predictive performance, with an AUC of 0.77 (95% CI: 0.70-0.83), sensitivity of 62.35%, and specificity of 78.29%, with a cut-off value of 143.8 ng/mL and a Youden index of 0.42." (PMID 40740239, 2025). "NRG1 can bind HER3 on tumor cells and promote HER2/HER3 signaling, engaging survival pathways such as PI3K–AKT under AR inhibition and thereby sustaining survival and fostering resistance to antiandrogen therapy." (PMID 41514658, 2025). "The result revealed that the serum NRG1, the NRG1 protein and mRNA levels in tumor tissue were positively correlated to the Gleason score, indicating the NRG1 levels were associated with the outcome of PC patients." (PMID 40740239, 2025). "The NRG1 FISH tests for the nine NRG1 FISH-positive cases resulted in 50% to 80% of positive tumor nuclei, all with single 3′-NRG1 FISH signals." (PMID 40723230, 2025). "NRG1 is a secretory protein and is reported to be involved in tumor growth, metastasis and drug resistance." (PMID 40959099, 2025). "Further analysis of receptor-ligand interactions highlighted the roles of KNG1_BDKRB2 and NRG1_ERBB4 signaling in promoting tumor aggression, suggesting potential therapeutic targets." (PMID 40969325, 2025). "Tumor regression was observed in 72% of the participants across multiple tumor types and NRG1 fusion partners, underscoring significant antitumor activity." (PMID 40571731, 2025). "Tumor genetic testing facilitates the identification of novel drug targets for patients with NRG1 fusions." (PMID 40730881, 2025). "NRG1 levels in tumor tissue, with a cutoff of 143.8 ng/mL, exhibit higher specificity (78.29%) and sensitivity (62.35%), making it particularly useful for identifying tumors at risk of progressing to CRPC and guiding timely intervention." (PMID 40740239, 2025). "Meanwhile, the serum NRG1 levels were also positively correlated to the relative NRG1 mRNA levels in tumor tissue." (PMID 40740239, 2025). "The cutoff values for NRG1 biomarkers-serum NRG1 levels (64.1 ng/mL), NRG1 levels in tumor tissue (143.8 ng/mL), and relative NRG1 mRNA expression in tumor tissue (1.353)-hold important clinical implications for predicting CRPC progression." (PMID 40740239, 2025).
tumor (continued). "NRG1 fusions are very uncommon across all tumor types and are infrequently documented in the medical literature." (PMID 39575425, 2024). "Knocking down NRG1 or using PI3K/AKT inhibitors resulted in a decrease in tumor count and an increase in overall survival in PDX mouse models." (PMID 38331905, 2024). "This study aimed to determine the significance of NRG1 as a novel diagnostic biomarker in BNST, emphasizing its involvement in the PI3K-Akt pathway and tumor immune regulation." (PMID 38331905, 2024). "All type B cases featured a single tumor cell remaining as one or more fusion cells, indicating the presence of at least one copy of NRG1." (PMID 38173003, 2024). "During a Phase II clinical trial (CRESTONE trial, NCT04383210), this anti-ERBB3 IgG2 monoclonal antibody produced an ORR of 33% across various tumor types harboring NRG1 fusions." (PMID 39575425, 2024). "In this study, we systematically gathered an assortment of tumor specimens with the objective of documenting the frequency of NRG1 rearrangements across diverse cancer types." (PMID 38173003, 2024). "NRG1 inhibits the occurrence of STAS by reducing tumor cell invasiveness and migratory capacity through the suppression of the AKT and ERK1/2 signaling pathways." (PMID 39830648, 2024). "NRG1 emerges as a potential diagnostic biomarker for BNST, influencing the PI3K-Akt pathway, and shaping the tumor immune microenvironment." (PMID 38331905, 2024). "Meanwhile, hypomethylation of several oncogenes such as NRG1, ITGB4 and GALNT6 associated with tumor-enriched bacteria suggests the potential of microbiota to promote host gene expression through epigenetic activation." (PMID 38589501, 2024). "Although NRG1 gene rearrangement is rare (~ 0.1–0.3%), it has been reported as a potentially actionable genomic event observed in various tumor types." (PMID 38173003, 2024). "More encouraging are the recently developed anti-ERBB/ERBB2/ERBB3 targeted therapies for the treatment of carcinomas harboring NRG1 fusions, as would be considered for our patient if her tumor were to eventually recur." (PMID 39575425, 2024). "In cancer, alterations in NRG1 expression can have significant implications for tumor growth and progression." (PMID 38957319, 2024). "Currently, afatinib is being explored prospectively in tumours with NRG1 fusions in the TAPUR (NCT02693535) and DRUP (NCT02925234) trials." (PMID 38347643, 2024). "NRG1 has been revealed fusions to exist at low frequencies across multiple tumor types, though the largest number of cases have been identified in NSCLC." (PMID 37770919, 2023). "Another factor secreted by MSCs that directly affects the growth of tumor cells is neuregulin 1 (NRG1)." (PMID 38022534, 2023). "The expression levels of CDKN2A were upregulated whereas GAP43, CPT2 and NRG1 were downregulated in tumor tissues of CRC patients." (PMID 37205121, 2023). "Out of 315 samples, 293 samples (93.0%) contained sufficient tumor tissue to allow evaluation of the NRG1 staining in cancer cells, and 289 samples (91.7%) were suitable to address the stromal expression." (PMID 36912192, 2023). "Neuromodulator 1 (NRG1) secreted by CAF can promote tumor cell resistance to antiandrogen therapy by activating HER3." (PMID 37784082, 2023). "Oncogenic gene fusion involving NRG1 contributes to the activation of ErbB-mediated pathways, representing a potential target for tumour management." (PMID 36925653, 2023). "We also modified the NRG1-based culture system and further developed it to grow benign and malignant tumor-derived salivary gland organoids." (PMID 35672412, 2022). "NRG1 fusions are enriched in aggressive mucinous adenocarcinoma of the lung, but have a low incidence in multiple tumor types." (PMID 36120374, 2022).
tumor (continued). "Engineered bivalent NRG1β exhibits reduced tumor potential compared to NRG1 and still retains its cardioprotective properties." (PMID 36120374, 2022). "MM-121 decreases tumour growth in pancreatic, ovarian (including cisplatin resistant models), prostate, kidney and NRG1-rearranged cancer models." (PMID 36271429, 2022). "Important open questions remain regarding how the tumor type, fusion partner of NRG1 and length of the fusion product affect the efficacy of zenocutuzumab." (PMID 36476337, 2022). "Neoplastic SCs within these tumors variably co-express ErbB kinases (which mediate the NRG1 response) with upregulated NRG1, suggesting the promotion of autocrine or paracrine survival and proliferation signaling pathways in tumor cells." (PMID 36139671, 2022). "More recently, Yoon et.al applied NRG1(neuregulin 1) to take place of EGF in tumor organoid media, to improve the luminal cell components for SGTs organoids." (PMID 36527158, 2022). "We found that concomitant high expression of HER3 and its ligand NRG1 in SCCHN is associated with the increased presence of regional lymphatic metastasis and the majority of HER3 is located on the differentiated tumor cells." (PMID 34465724, 2021). "Tumor-agnostic therapies for cancer patients with biomarkers RET fusion, HER2, FGFR mutations, KRAS mutations, ROS1, ALK, G12C, neuregulin 1 (NRG1) fusion, PD-L1 overexpression, and APOBEC alteration are under consideration." (PMID 33670524, 2021). "Although NRG1 appears to be oncogenic in some tumours, it is inactivated in carcinomas at least as often as it is activated." (PMID 33413557, 2021). "Mapping the loss of 8p in cancer cells revealed that almost all the translocation breaks were proximal to NRG1, making it a candidate tumor suppressor gene." (PMID 34068503, 2021). "CRC is an NRG1 fusion-positive tumor, in which the expression of NRG1 III is significantly upregulated and negatively correlated with lymph node metastasis, implying a satisfactory prognosis." (PMID 34898475, 2021). "A phase II clinical trial aims to investigate the efficacy of the pan-ERBB inhibitor afatinib in advanced-stage NRG1-rearranged malignancies across all tumor entities following progression in standard therapy (NCT04410653)." (PMID 34680187, 2021). "We examined levels of RTK ligands, HGF and NRG1, and found significant upregulation of these ligands in tumor tissue from erlotinib-treated mice in both A549 and HCC827 tumors." (PMID 34853306, 2021). "The paracrine factors such as TNF, WNT10A, PDGFA, and NRG1 were also elevated in tumor-infiltrating dendritic cells." (PMID 32434423, 2020). "Currently TNF, WNT10A, PDGFA, and NRG1 secreted by infiltrated dendritic cells in the tumor microenvironment were identified to be likely involved in the neuropathic pain using RNA-seq, scRNA-seq, and ChIP-seq data." (PMID 32434423, 2020). "The authors identified neuregulin 1 (NRG1) as a factor secreted by the stroma during hormone therapy that can signal to the HER3 receptor expressed by tumor cells." (PMID 33291749, 2020). "In other cases NRG1 was shown to be produced by the same tumour cells and to induce ErbB3 phosphorylation via an autocrine lop." (PMID 31557826, 2019). "The third tumor had a fusion at the NRG1 gene, a ligand for HER3 and HER4 receptors that was highly expressed at the protein level." (PMID 30499260, 2019). "By hijacking NRG1 addiction of cancer cells to promote its inhibitory effects on NRG1-mediated tumor growth and resistance, the allosteric non NRG1-competing 9F7-F11 displays a unique potential for targeted treatment of NRG1-positive cancers." (PMID 31443721, 2019). "The binding to HER3 and biological effects on tumor cells of 9F7-F11 are paradoxically facilitated by the natural ligand NRG1." (PMID 31443721, 2019). "Sequencing of the original tumor revealed a major chromothriptic event on chromosome 8 that involved the NRG1 gene, a known ligand for HER3 and HER4 receptors." (PMID 30499260, 2019).